CPEB1 (cytoplasmic polyadenylation element binding protein 1)
Diseases named in the same sentence as CPEB1 in open-access papers (continued):
Sharing a sentence is not in itself a finding about the gene and the disease.
infection (4 papers, 2017 to 2023). The state of being infected such as from the introduction of a foreign agent such as serum, vaccine, antigenic substance or organism. "Collectively HCMV poly(A)‐tails were also shown to be sensitive to levels of CPEB1, a cytoplasmic RNA‐BP upregulated in infection which recruits cytoplasmic poly(A)‐polymerases to extend poly(A)‐tails." (PMID 37846490, 2023). "Staining of RGCs indicated a similar infection efficiency for AAV-Cpeb1-HA (79%) and the control AAV-Gfp (70%), and overexpression of Cpeb1 was verified by staining." (PMID 29379413, 2017). "Decreased transcription levels of CPEB1 reduced viral RNA polyadenylation (shortening poly-A tails), alternative splicing and other RNA processing events, which leaded to a decrease of HCMV titers and shift in the transcription profile in comparison with a mock infection." (PMID 30604286, 2019).
CPEB1 also shares sentences with these, for which no sentence is quoted: autism spectrum disorder (3 papers); cyst (2); endothelial dysfunction (2); Huntington disease (2); memory impairment (2); Obesity (2); osteosarcoma (2); Alpha Thalassemia/Mental Retardation Syndrome X-linked (1); Ataxia (1); atherosclerosis (1); attention deficit-hyperactivity disorder (1); bipolar disorder (1); Brain Tumor (1); Cerebral ischemia (1); epilepsy (1); generalized anxiety disorder (1); liver diseases (1); metabolic disorders (1); multiple myeloma (1); neuropathy (1); non-alcoholic steatohepatitis (1); obsessive-compulsive disorder (1); oligodendroglioma (1); oral lichen planus (1); osteoarthritis (1); ovarian serous cystadenocarcinoma (1); pancreatic adenocarcinoma (1); rectal cancer (1); schistosomiasis (1); temporal lobe epilepsy (1).
A further 2 diseases each share a sentence with CPEB1 in 1 paper.